SFMBT1 (Scm like with four mbt domains 1)
Description:
Histone-binding protein, which is part of various corepressor complexes. Mediates the recruitment of corepressor complexes to target genes, followed by chromatin compaction and repression of transcription. Plays a role during myogenesis: required for the maintenance of undifferentiated states of myogenic progenitor cells via interaction with MYOD1. Interaction with MYOD1 leads to the recruitment of associated corepressors and silencing of MYOD1 target genes. Part of the SLC complex in germ cells, where it may play a role during spermatogenesis.
Synonyms: hSFMBT; RU1; DKFZp434L243; SFMBT
Tractability: PROTAC: ubiquitination databases record sites on it.
Target class: Methyl-lysine/arginine binding protein; MBT domain; Epigenetic regulator; Reader
Gene: Protein-coding gene on chromosome 3 (52,903,564 to 53,046,750, reverse strand). Ensembl gene ENSG00000163935.
Subcellular location: Nucleus
Subcellular location (Human Protein Atlas): Nucleoplasm
Gene Ontology:
Molecular function: histone binding; protein binding; chromatin binding; transcription corepressor activity
Biological process: negative regulation of DNA-templated transcription; negative regulation of muscle organ development; regulation of DNA-templated transcription
Cellular component: nucleoplasm; nucleus
Genetic constraint (gnomAD): Loss-of-function variants: 29 observed, 98.33 expected, observed/expected ratio (o/e) 0.29, 90% interval 0.22 to 0.4. The upper end of that interval is the gene's LOEUF score, 0.4, which puts it in group 1 of 6, group 1 being the genes least tolerant of losing a copy. Missense variants: 755 observed, 1,036.8 expected, observed/expected ratio (o/e) 0.73, 90% interval 0.69 to 0.77. Synonymous variants: 321 observed, 368.53 expected, observed/expected ratio (o/e) 0.87, 90% interval 0.79 to 0.95.
Homologues: Orthologues: chimpanzee SFMBT1 (99% identical), macaque SFMBT1 (99% identical), dog SFMBT1 (97% identical), pig SFMBT1 (96% identical), rabbit SFMBT1 (92% identical), mouse Sfmbt1 (89% identical), rat Sfmbt1 (89% identical), guinea pig SFMBT1 (88% identical), zebrafish SFMBT1 (64% identical), tropical clawed frog sfmbt1 (57% identical), Drosophila melanogaster l(3)mbt (12% identical), Drosophila melanogaster Sfmbt (11% identical), and 2 more. Paralogues in human: SFMBT2 (55% identical), SCMH1 (21% identical), SCML2 (20% identical), L3MBTL3 (14% identical), L3MBTL1 (14% identical), L3MBTL4 (14% identical), PHC2 (12% identical), PHC1 (12% identical), L3MBTL2 (12% identical), PHC3 (11% identical), MBTD1 (11% identical), SCML4 (10% identical), and 6 more.
Diseases named in the same sentence as SFMBT1 in open-access papers:
SFMBT1 is named in the same sentence as 28 diseases in open-access papers, as found by Europe PMC text mining. Sharing a sentence is not in itself a finding about the gene and the disease. The quoted sentences say what the papers report.
schizophrenia (4 papers, 2020 to 2025). A major psychotic disorder characterized by abnormalities in the perception or expression of reality. "One example shows that genetic variant rs2535629 confers risk of schizophrenia by mutating a CTCF binding site near the promoter of SFMBT1." (PMID 37324587, 2023). "Our eQTL analysis showed that rs2535629 was associated with the expression of GLT8D1, NKE4, and SFMBT1 in the human brain, suggesting that rs2535629 may confer schizophrenia risk by modulating these genes." (PMID 34978167, 2022). "Our study identified rs2535629 as a likely causal variant (for schizophrenia) at the 3p21.2 risk locus and demonstrated that this functional variant regulates SFMBT1 expression by affecting CTCF binding, offering pivotal insights into genetic mechanisms and pathogenesis of schizophrenia." (PMID 34978167, 2022). "Of note, gene expression showed that SFMBT1 was dysregulated in neurons induced from fibroblasts of schizophrenia cases compared with controls, and rs2535629 physically interacts with SFMBT1, supporting that this functional variant confers risk of schizophrenia by modulating SFMBT1 expression." (PMID 34978167, 2022). "Taken together, these data suggested that the functional regulatory variant rs2535629 might confer schizophrenia risk by regulating SFMBT1." (PMID 34978167, 2022). "In summary, we elucidated the molecular regulatory mechanism of the schizophrenia risk variant rs2535629 at the single‐nucleotide resolution level, and we showed that rs2535629 may confer schizophrenia risk by regulating SFMBT1 expression (a gene about 104 kb away)." (PMID 34978167, 2022). "In addition to GLT8D1 and NEK4, our study also suggests that SFMBT1 may be a potential risk gene at this locus, and functional SNP rs2535629 may confer schizophrenia risk by regulating SFMBT1." (PMID 34978167, 2022). "Interestingly, differential expression analysis of GLT8D1, SFMBT1, and NEK4 suggested that rs2535629 may confer schizophrenia risk by regulating SFMBT1 expression." (PMID 34978167, 2022). "It is further demonstrated that Sfmbt1 regulates neurodevelopment and dendritic spine density, two key pathological characteristics of schizophrenia." (PMID 34978167, 2022). "However, SFMBT1 was significantly down‐regulated in neurons induced from schizophrenia cases compared with controls (P = 8.90 × 10−4, FDR<0.05)." (PMID 34978167, 2022). "More work is needed to further elucidate the role of rs2535629 and SFMBT1 in schizophrenia." (PMID 34978167, 2022). "In addition, more work (e.g., animal model) is needed to investigate the role and mechanisms of SFMBT1 dysregulation in schizophrenia pathogenesis." (PMID 34978167, 2022). "Finally, we explored the potential roles of Sfmbt1 in schizophrenia pathogenesis by using the neural stem cell model (including proliferation and differentiation of neural stem cells) and dendritic spine density analysis." (PMID 34978167, 2022). "Transcriptome analysis also support the potential role of Sfmbt1 in schizophrenia pathogenesis." (PMID 34978167, 2022). "To further test if rs2535629 conferred schizophrenia risk by modulating the expression of NEK4, GLT8D1, and SFMBT1, we examined the expression level of these three genes in brains of schizophrenia cases and controls using data from the PsychENCODE (559 cases and 936 controls)." (PMID 34978167, 2022). "Fourth, considering that rs2535629 is associated with the expression of GLT8D1, NEK4, and SFMBT1, we could not rule out the possibility that rs2535629 might confer schizophrenia risk by regulating the expression of GLT8D1 and NEK4." (PMID 34978167, 2022). "We found that Sfmbt1 not only regulated proliferation and differentiation of NSCs, but also affected the dendritic spine density of neurons, implicating that this gene may be involved in schizophrenia pathophysiology by affecting neurodevelopment and synaptic transmission." (PMID 34978167, 2022).
schizophrenia (continued). "As we have demonstrated the potential role of GLT8D1 in schizophrenia in our previous study and expression analysis showed no significant change of NEK4 and GLT8D1 in schizophrenia cases compared with controls, we focused on SFMBT1 in this study." (PMID 34978167, 2022).
cervical cancer (3 papers, 2016 to 2019). A primary or metastatic malignant neoplasm involving the cervix. "The results showed that knockdown of SFMBT1 or DCUN1D1 inhibited invasion of cervical cancer cell similarly as those that were observed in miR-218 overexpression treatment." (PMID 27285984, 2016). "In total, we suggest that HPV16 E6 may promote the metastasis of cervical cancer by repressing miR-218 expression, and then promote the expression of SFMBT1 and DCUN1D1." (PMID 27285984, 2016). "Considering our own findings as well as those that have been previously published, we speculate that miR-218 might inhibit the invasion and metastasis of cervical cancer by targeting SFMBT1." (PMID 27285984, 2016). "MiR-218 was also found to inhibit epithelial-mesenchymal transition (EMT), migration, and invasion by targeting SFMBT1 and DCUN1D1, and was downregulated in cervical cancer." (PMID 31310241, 2019). "The overexpression of SFMBT1 induced EMT and increased the migration and invasiveness of cervical cancer cells, while the overexpression of DCUN1D1 increased the migration and invasiveness of these cells, but did not induce EMT." (PMID 27285984, 2016). "This suggests that the decrease in SFMBT1 and DCUN1D1 expression is required for the decrease in the invasiveness of miR-218-overexpressing cervical cancer cells." (PMID 27285984, 2016). "In accordance with these results, we found a clear decrease in endogenous SFMBT1 and DCUN1D1 protein expression in cervical cancer cells when miR-218 was overexpressed." (PMID 27285984, 2016). "Here, we found that HPV16 E6 promotes EMT and enhances the invasiveness of cervical cancer cells, which is consistent with the effects of SFMBT1 and DCUN1D1 and is contrary to the effect of miR-218 on cervical cancer metastasis." (PMID 27285984, 2016). "Our results showed that SFMBT1, as the direct and functional target of miR-218, promotes EMT and invasion in cervical cancer, which establishes SFMBT1 as a critical promoter of metastasis." (PMID 27285984, 2016). "Taken together, our results revealed that HPV16 E6 promoted EMT and invasion in cervical cancer via the repression of miR-218, while miR-218 inhibited EMT and invasion in cervical cancer by targeting SFMBT1 and DCUN1D1." (PMID 27285984, 2016). "Importantly, HPV16 E6 downregulated the expression of miR-218 in cervical cancer, while miR-218 rescued the promotion effect of HPV16 E6 on the expression of SFMBT1 and DCUN1D1." (PMID 27285984, 2016). "To determine whether SFMBT1 and DCUN1D1 serve as critical mediators in the role of miR-218 on cervical cancer, we knocked down SFMBT1 and DCUN1D1 by the application of synthetic siRNA in SiHa and HeLa cells." (PMID 27285984, 2016). "Moreover, we identified SFMBT1 and DCUN1D1, which are responsible for the metastasis of cervical cancer, as the direct functional targets of miR-218." (PMID 27285984, 2016). "The role of SFMBT1 in cervical cancer has not been reported in previous studies." (PMID 27285984, 2016).
bipolar disorder (2 papers, 2022 to 2025). A disorder of the brain that causes unusual shifts in mood, energy, activity levels and the ability to carry out day-to-day tasks. "rs2535629 might confer risk of bipolar disorder by regulating SFMBT1." (PMID 34978167, 2022).
brain tumor (2 papers, 2016 to 2017). "The SFMBT1 gene encodes a protein containing four malignant brain tumor repeat domains." (PMID 28789618, 2017). "SFMBT1 belongs to the malignant brain tumor (MBT) domain-containing protein family, which contributes to multiple cellular processes, including cell proliferation and maintenance of the characteristics of stem cells." (PMID 27285984, 2016).
colon carcinoma (2 papers, 2020 to 2022). "Consistent with in vitro experimental results, SFMBT1 promotes cancer tumorigenesis and 5-FU resistance of colon cancer in vivo." (PMID 35577773, 2022). "Consistent with in vitro experimental results, HMG20A in combination with SFMBT1 drive colon cancer tumorigenesis and 5-FU resistance in vivo." (PMID 35577773, 2022). "To investigate the role of SFMBT1 in colon cancer, we first examined its expression in human colon cancer tissues." (PMID 35577773, 2022). "Given TCGA and GEPIA database information of SFMBT1 and HMG20A in cancer, we speculated that HMG20A might be involved in colon cancer tumorigenesis and drug resistance with SFMBT1." (PMID 35577773, 2022). "To investigate the function of HMG20A in combination with SFMBT1 in colon cancer in vivo, we studied xenograft tumors derived from HCT-116/5-FU cell transfected with SCR, sh-HMG20A, sh-HMG20A + scr and sh-HMG20A + sh-SFMBT1." (PMID 35577773, 2022).
diabetes (2 papers, 2016 to 2020). "This indicates that diabetes might be one potential trigger that is needed for the CN loss in intron 2 of SFMBT1 to cause iNPH and raises a question for further study on the potential gene-environmental interactions." (PMID 32933532, 2020). "The SFMBT1 CN loss might require some other unknown external factor to trigger the development of iNPH, and interestingly in this study, diabetes was present in 3 out of the 4 probable fNPH patients that had CN loss in the SFMBT1 gene compared to none out of 2 of the non-iNPH relatives." (PMID 32933532, 2020).
Hypertension (2 papers, 2012 to 2017). The presence of chronic increased pressure in the systemic arterial system. "The molecular mechanism by which genetic variants of SFMBT1 gene contribute to hypertension risk remains unknown." (PMID 28120895, 2017). "Four hypertension susceptibility genes, IGF1, SLC4A4, WWOX, and SFMBT1, were found by a statistical permutation procedure, confirmed by gene expression analysis, and further replicated using data from the HKHS." (PMID 22479346, 2012). "SFMBT1, which encodes the scm-like with four MBT domains protein 1, is a novel hypertension gene." (PMID 22479346, 2012).
malignant brain tumor (2 papers, 2012 to 2016). "The SFMBT1 gene encodes a protein with 866 amino acid residues, which contains four malignant brain tumor (MBT) repeat domains." (PMID 27861535, 2016).
psoriasis (2 papers, 2020). An autoimmune condition characterized by red, well-delineated plaques with silvery scales that are usually on the extensor surfaces and scalp. "Loss of miR-20a-3p plays a role in psoriasis by targeting scm-like with four mbt domains 1 (SFMBT1) underlying multiple cellular phenomena, including cell proliferation." (PMID 32806619, 2020). "Moreover, keratinocytes are rekated to cell apoptosis in psoriasis, and inhibition of cell apoptosis contribute to the amelioration of psoriasis (MiR-20a-3p regulates TGF-β1/Survivin pathway to affect keratinocytes proliferation and apoptosis by targeting SFMBT1 in vitro)." (PMID 32650835, 2020).
metabolic syndrome (1 paper, 2022). A cluster of metabolic risk factors for CARDIOVASCULAR DISEASES and TYPE 2 DIABETES MELLITUS. "Examples of validated variants within microRNAs included in this catalog are miR-196a2 variant rs11614913 regulating SFMBT1 and HOXC8 in metabolic syndrome, and miR-4513 variant rs2168518 regulating GOSR2 in cardiometabolic diseases." (PMID 35365203, 2022).
cancer (8 papers, 2016 to 2024). A tumor composed of atypical neoplastic, often pleomorphic cells that invade other tissues. "TCGA shows the expression of SFMBT1 in tumor tissues and adjacent normal tissues or in different stages of cancer." (PMID 35577773, 2022).
tumor (7 papers, 2016 to 2026). "Scm-like with four malignant brain tumor domains 1 (SFMBT1) is up-regulated in CRC tumor tissues and cells and may be associated with drug resistance." (PMID 35577773, 2022). "After discovering that SFMBT1 was expressed at higher levels in tumor tissues, we determined its expression in human colorectal epithelial cells and CRC cell lines." (PMID 35577773, 2022). "Knockdown of HMG20A significantly reduced tumor volume and tumor growth, which were further reduced after SFMBT1 knockdown." (PMID 35577773, 2022). "The glandular regions in the CRC tumor tissues are poorly differentiated compared to normal tissue with clusters of tumor cells overexpressing SFMBT1." (PMID 35577773, 2022). "Expression of SFMBT1 was also examined in CRC by immunohistochemistry (IHC) in tumor tissues and tissue microarrays." (PMID 35577773, 2022). "Our study shows that miR-218, as a tumor suppressor miRNA, also is a negative regulator of the pro-metastasizing genes SFMBT1 and DCUN1D1." (PMID 27285984, 2016). "Xenograft experiments were conducted to investigate the role of SFMBT1 and HMG20A in tumor growth and metastasis in vivo." (PMID 35577773, 2022).
neurological diseases (1 paper, 2022). "Collectively, these results indicate that Sfmbt1 regulates important pathways related to neuronal‐related cell components and neurological diseases, further indicating the important role of Sfmbt1 in the CNS." (PMID 34978167, 2022).
SFMBT1 also shares sentences with these, for which no sentence is quoted: colorectal cancer (2 papers); oesophageal cancer (2); sarcopenia (2); autism (1); bone tumor (1); brain diseases (1); cerebrovascular disease (1); clear cell renal cell carcinomas (1); Cognitive impairment (1); lung carcinoma (1); melanoma (1); osteosarcoma (1); pancreatic ductal adenocarcinoma (1); Urinary incontinence (1); Ventriculomegaly (1).